CAV1 (caveolin 1)
Diseases named in the same sentence as CAV1 in open-access papers (continued):
Sharing a sentence is not in itself a finding about the gene and the disease.
brain injury (4 papers, 2018 to 2024). Acute and chronic (see also brain INJURIES, CHRONIC) injuries to the brain, including the cerebral hemispheres, CEREBELLUM, and brain STEM. "To further unravel the transport across the BBB that is being altered, we analyzed the protein levels of endothelial claudin-5 and caveolin-1 (Cav-1), the latter has been associated with brain injury-related BBB breakdown." (PMID 30687711, 2018). "In cerebral pathologies such as ischemic brain injury, cerebral hemorrhage, and cerebral edema, increased expression of Cav-1 contributes to increased BBB permeability, exacerbating symptoms of brain injury." (PMID 38922036, 2024). "The impact of Ang-1 on caveolin-1 expression was demonstrated recently in rats, where increased caveolin-1 levels following acute brain trauma were reversed with Ang-1 treatment." (PMID 34702292, 2021). "It has also been found that CAV-1 exhibits positive effects during specific brain injuries." (PMID 36253854, 2022). "Altogether, alterations in the secretion of Ang-1 (from brain vascular mural cells) or Ang-2 (from brain endothelia) following brain injury could influence endothelial transcytosis by modulating the Mfsd2a/caveolin-1 pathway." (PMID 34702292, 2021).
channelopathies (4 papers, 2017 to 2024). "Understanding the different mechanistic effect of Cav1 mutations reveals that effective therapeutic approaches for X-linked Cav1.4 diseases will be different from autosomal Cav1.1–1.3 channelopathies." (PMID 33584831, 2021). "Single-twitch and tetanic stimulation of extensor digitorum longus (EDL) muscle showed a similar reduction of maximum force in single-channelopathy (ClC-1–/–, blue) and bi-channelopathy (CaV1.1Δe29 ClC-1–/–, red) muscle as compared with WT mouse muscle (black) and CaV1.1Δe29 (orange) controls." (PMID 38165038, 2024). "Loss of function variants in channelopathy genes potassium two pore domain channel (KCNK3) and ATP-binding cassette subfamily member 8 (ABCC8), as well as membrane reservoir gene caveolin-1 (CAV1), are causative for PAH." (PMID 33971972, 2021). "Encouraged by the results from SNc modeling that the dysregulated CaV1.3, Ca2+ influx and pacemaking could be corrected back to normal, we expect CMI and its therapeutic potentials to manifest in diverse pathophysiology including CaV1 channelopathies." (PMID 28059704, 2017).
chronic lymphocytic leukemia (4 papers, 2015 to 2021). "However, over-expression of CAV1 was associated with immune tolerance in chronic lymphocytic leukemia cells." (PMID 32923385, 2020). "We have shown CAV1 to be significantly dysregulated across more than 67% of cases of mature T-cell lymphomas as well as in aggressive cases of chronic lymphocytic leukemia." (PMID 28018857, 2016). "Specifically, CAV1 is downregulated in SMZL cases, while upregulated in aggressive cases of chronic lymphocytic leukemia and five types of mature T-cell lymphomas." (PMID 28018857, 2016). "Herein, presented are the findings of the genetic analysis with an increased focus on caveolin-1 (CAV1), a gene seen heterogeneously upregulated across all T-cell lymphoma subtypes, mimicking data observed in chronic lymphocytic leukemia, a B-cell neoplasm." (PMID 26566034, 2015).
Congenital generalized lipodystrophy type 3 (4 papers, 2015 to 2025). Any congenital generalized lipodystrophy in which the cause of the disease is a mutation in the CAV1 gene. "An example is a homozygous knockout in caveolin 1, Cav1, which is linked by orthology to Berardinelli-Seip congenital lipodystrophy (ORPHA:528), a rare condition affecting the endocrine system." (PMID 31986132, 2020).
coronary artery disease (4 papers, 2017 to 2022). "The Tiaopi Huxin recipe, a traditional Chinese medicine widely used to treat coronary heart disease, was recently shown to decrease the expression of caveolin-1, thereby improving endothelial function and reducing atheromatous lesions in ApoE-/- mice." (PMID 32257548, 2020). "The cardioprotective effects of Cav-1 in ischemic heart disease have been well reported in both mouse and human specimens; an increase of Cav-1 in an infarcted area was detected in the early stage of MI." (PMID 31178960, 2019).
Crohn disease (4 papers, 2015 to 2025). A gastrointestinal disorder characterized by chronic inflammation involving all layers of the intestinal wall, noncaseating granulomas affecting the intestinal wall and regional lymph nodes, and transmural fibrosis. "Decreased Cav-1 expression has been observed in both stenotic colonic tissues of Crohn’s disease patients and fibrotic intestinal tissues of dextran sodium sulfate-induced mice." (PMID 41030451, 2025). "In two datasets, Cav-1 expression was higher in patients with ulcerative colitis (UC) and Crohn's disease (CD) than that of each control." (PMID 32461676, 2020). "Current research has implicated a close correlation between key ferroptosis-related genes such as TIMP1, CAV1, CD44, HIF1A, and IFNG, and immune infiltration in Crohn’s disease." (PMID 40687427, 2025). "Overexpression of Cav-1 can inhibit autophagy by increasing the expression of SQSTM1/p62, and then suppress the activation of fibroblasts, thereby alleviating Crohn’s disease-induced intestinal fibrosis." (PMID 41030451, 2025).
depression (4 papers, 2010 to 2023). "According to our results, increased adherence to N6/N3 ratio in the interaction with CAV1 genotype (AG-alleles carriers) leads to a positive interaction on depression." (PMID 37311812, 2023). "Apart from that, CAV-1 expression has been shown to be involved in depression and CAV-1 knockdown could reverse the development of this disorder." (PMID 37542261, 2023).
ductal carcinoma in situ (4 papers, 2017 to 2024). "Poor prognosis is associated with the loss of stromal Cav1 in the fibroblast of ductal carcinoma in situ (DCIS), gastric cancer, and prostate cancer." (PMID 38361760, 2024). "Similar work confirmed that stromal Cav-1 loss was specifically associated with early ductal carcinoma in situ (DCIS) progression to invasive breast cancer, with shorter time to recurrence and higher recurrence rate." (PMID 28546853, 2017). "More specifically, it was shown that loss of stromal CAV1 expression accelerates the progression of ductal carcinoma in situ to invasive cancer and is associated with more advanced disease with higher T and N stages, higher recurrence rates, and decreased DFS and OS8, 9, 17–21." (PMID 28515480, 2017).
epilepsy (4 papers, 2017 to 2022). A brain disorder characterized by episodes of abnormally increased neuronal discharge resulting in transient episodes of sensory or motor neurological dysfunction, or psychic dysfunction. "The GOF in the Cav1.3S variant with high neuronal expression is likely to result in epilepsy, whereas the LOF in the long Cav1.3L variant results in sinus node dysfunction." (PMID 36430690, 2022). "This systematic review aims to assess the effect of cinnamaldehyde on Cav-1 and Survivin expression in epilepsy." (PMID 32501993, 2020). "Several studies have reported the effect of cinnamaldehyde on Cav-1 and Survivin expression in epilepsy." (PMID 32501993, 2020). "Its findings will provide helpful evidence for the effect of cinnamaldehyde on Cav-1 and Survivin expression in epilepsy." (PMID 32501993, 2020). "Thus, this study will explore the effect of cinnamaldehyde on Cav-1 and Survivin expression in epilepsy." (PMID 32501993, 2020). "This systematic review will investigate whether cinnamaldehyde is effective on Cav-1 and Survivin expression in epilepsy." (PMID 32501993, 2020). "Therefore, this study will systematically appraise the effect of cinnamaldehyde on Cav-1 and Survivin expression in epilepsy." (PMID 32501993, 2020). "The levels of serum VILIP-1, neuron-specific enolase (NSE) and caveolin-1 (CAV-1) were measured to investigate potential of VILIP-1 as a biomarker for seizure-induced neuronal injury, and the correlation of VILIP-1 with severity of epilepsy and blood-brain barrier dysfunction were investigated." (PMID 33071949, 2020).
Hepatitis (4 papers, 2018 to 2025). Inflammation of the liver. "ONOO•-mediated ferroptosis is implicated in concanavalin A-induced hepatitis and this process can be inhibited by caveolin-1 (CAV1), a scaffolding protein binding to NOS3/eNOS81." (PMID 33268902, 2021). "Despite a number of reports describing the regulatory role of Cav‐1 under various physiological and pathological conditions, whether Cav‐1 participates in LPS‐induced hepatic injury during acute inflammation and hepatitis remains to be explored." (PMID 30134043, 2018). "Moreover, the absence of CAV1 exacerbated the susceptibility to ConA-induced hepatitis by decreasing SLC7A11 levels." (PMID 40180904, 2025).
HIV-1 infection (4 papers, 2014 to 2022). The type species of lentivirus and the etiologic agent of acquired immunodeficiency syndrome (AIDS). "Tat, a specific HIV protein, causes high expression of CAV-1 and thus restricts HIV-1 infection." (PMID 32357558, 2020). "Since CAV-1 plays multiply roles during HIV-1 infection and pathogenesis, CAV-1 can be used as a target for the treatment of HIV infection." (PMID 32357558, 2020). "Altogether, these data strongly indicate an important protective role for caveolar uptake and for the caveolar protein caveolin-1 in limiting HIV-1 infection in LCs." (PMID 25551286, 2014). "We investigated the internalization route of HIV-1 and the role of caveolin-1 dependent internalization in protection against HIV-1 infection in LCs." (PMID 25551286, 2014). "Here, we show that BGs are caveolin-1-positive vesicles and that caveolin-1 prevents HIV-1 infection in human Langerhans cells." (PMID 25551286, 2014). "For instance, as CAV-1 can restrict HIV-1 infection, CAV-1 mimetics or analogs may be used to treat HIV-1 infection." (PMID 32357558, 2020). "Thus, our data strongly indicate that BGs belong to the caveolar endocytosis pathway and that caveolin-1 mediated HIV-1 uptake is an intrinsic restriction mechanism present in human LCs that prevents HIV-1 infection." (PMID 25551286, 2014).
Huntington disease (4 papers, 2018 to 2020). Huntington disease (HD) is a rare neurodegenerative disorder of the central nervous system characterized by unwanted choreatic movements, behavioral and psychiatric disturbances and dementia. "The loss of caveolin-1 expression in a knock-in mouse model of Huntington’s disease suppresses the pathophysiology in vivo—a protective effect that might also be related to a decrease in the OCTN2 plasma membrane expression." (PMID 33050117, 2020). "Our main results show that in a mouse model of Huntington’s disease, Cav1 channels may be dysfunction." (PMID 31216184, 2019).
inflammatory bowel disease (4 papers, 2012 to 2025). A spectrum of small and large bowel inflammatory diseases of unknown etiology. "Thus, Cav-1 expressed in ECs could be considered as a potential therapeutic target for inflammatory bowel disease." (PMID 26605130, 2012). "Caveolin-1 (CAV1), a pivotal protein implicated in endothelial cell-mediated angiogenesis, assumes an ambiguous role with elusive underlying mechanisms in the pathogenesis of inflammatory bowel disease (IBD)." (PMID 40877233, 2025).
intervertebral disc degeneration (4 papers, 2008 to 2016). "No matter what reason it is, however, further studies are warranted to evaluate the role of caveolin-1 in disc degenerative disease." (PMID 25298000, 2014).
liver cirrhosis (4 papers, 2015 to 2023). "Our results showed that the expression of cell adhesion molecules, such as CDH1, PECAM1, SELL and CAV1, which are canonical molecules in cell adhesion, was evidently changed in liver cirrhosis." (PMID 34434654, 2021).
metastasis (4 papers, 2015 to 2024). The spread or migration of cancer cells from one part of the body (where they first appeared) to another. "Furthermore, the majority of patients with pulmonary metastasis (27/38, 71.1%; P < 0.001) had both high MIM-B expression and high caveolin-1 expression." (PMID 29221140, 2017). "In our study, only Cav1 expression in brain metastasis, and not in the primary tumor, was correlated with poor prognosis and an increased risk of death in the multivariate model, demonstrating its value as an independent prognosticator." (PMID 26315660, 2015).
Myocardial fibrosis (4 papers, 2018 to 2022). "The caveolin-1 scaffolding domain (CSD, amino acids 82–101 of caveolin-1) has been shown to suppress bleomycin-induced lung and skin fibrosis and angiotensin II (AngII)-induced myocardial fibrosis." (PMID 35213624, 2022). "In the present study, BHD reduced the myocardial fibrosis and inflammation, promoted angiogenesis in the infarction border zone via Cav-1/VEGF signaling pathway, then reduced the MI size, and improved the cardiac function." (PMID 31178960, 2019). "We showed recently that myocardial fibrosis and the loss of cardiac function in mice with transverse aortic constriction (TAC) could be averted by treatment with the caveolin-1 scaffolding domain (CSD) peptide." (PMID 30576317, 2018).
Nephropathy (4 papers, 2015 to 2023). A nonspecific term referring to disease or damage of the kidneys. "The goal of this study is to investigate whether YBT could alleviate Adriamycin-induced nephropathy edema and reduce renal microvascular permeability by inactivating the Cav-1/eNOS pathway." (PMID 37229256, 2023). "Our results showed that patients receiving a graft with CAV1 AA genotype significantly developed more interstitial fibrosis lesions (ci = 1 and ci = 2) and are more prone to experience kidney damages (evaluated by both proteinuria and decrease of glomerular filtration rate) over time." (PMID 25945124, 2015).
neuropathy (4 papers, 2017 to 2020). A disorder affecting the nervous system that manifests with pain, tingling, numbness, and/or muscle weakness. "On the other hand, reduced expression of Caveolin-1 in monocytes was inversely correlated with Toll-like receptor (TLR) 4 levels in T2DM and neuropathy patients suggesting that low CAV1 expression in white cells could aggravate the TLR4-mediated inflammatory cascade." (PMID 32125224, 2020). "In vivo, CAV1 expression in monocytes from diabetic patients decreased, while TLR4 and TNF-α secretion increased and even more significantly in diabetic patients with neuropathy, suggesting, a role of CAV1 in regulating TLR4-mediated inflammatory cascade in T2DM." (PMID 32082483, 2020).
partial lipodystrophy (4 papers, 2008 to 2019). Loss and redistribution of subcutaneous and/or visceral adipose tissue from specific regions of the body. "We found a heterozygous frameshift mutation in CAV1, designated I134fsdelA-X137, in a female patient who had atypical partial lipodystrophy, with subcutaneous fat loss affecting the upper part of her body and face, but sparing her legs, gluteal region and visceral fat stores." (PMID 18237401, 2008).
preeclampsia (4 papers, 2019 to 2025). Preeclampsia is a hypertensive disorder of pregnancy that is characterized by new-onset hypertension with proteinuria presenting after 20 weeks of gestation, and depending on mild or severe forms may initially present with severe headache, visual disturbances, and hyperreflexia. "Furthermore, CAV1 has been implicated in the mechanism of oedema in preeclampsia (PE) following hypoxia of trophoblasts through the HMGB1/TLR4/CAV-1 pathway." (PMID 32028606, 2020). "In this study, we identified several central genes closely related to ferroptosis in STB-EVs (ALB, NOX4, CDKN2A, TXNRD1, and CAV1) that are potential biomarkers related to ferroptosis in preeclampsia." (PMID 36343018, 2022). "In this investigation, we demonstrated numerous key genes (ALB, NOX4, CDKN2A, TXNRD1, and CAV1) that are expected to act as biomarkers for ferroptosis in STB-EVs of preeclampsia." (PMID 36343018, 2022). "ALB, NOX4 and CAV1 are associate with the prosses of preeclampsia, and the other two genes (CDKN2A, TXNRD1) have not been linked directly to the occurrence of preeclampsia." (PMID 36343018, 2022). "Furthermore, in research on the pathophysiology of pre-eclampsia (PE), hypoxic trophoblasts displayed higher intracellular HMGB1 protein levels which could increase TLR4 and Caveolin-1." (PMID 31284269, 2019).
pulmonary edema (4 papers, 2014 to 2019). Accumulation of fluid in the lung tissues causing disturbance of the gas exchange that may lead to respiratory failure. "The study suggests that Cav-1 may be a novel potential target for preventing pulmonary edema at an early stage of BPD." (PMID 27176222, 2016). "Pulmonary vascular barrier function, regulated in part by Src kinase-dependent phosphorylation of caveolin-1 and intercellular adhesion molecule-1 (ICAM-1), plays a crucial role in the development of protein-/neutrophil-rich pulmonary edema, the hallmark of ALI." (PMID 25097454, 2014).
sarcopenia (4 papers, 2020 to 2025). Progressive decline in muscle mass due to aging which results in decreased functional capacity of muscles. "To date, studies focusing on genes associated with sarcopenia itself are rare; only the influences of the genetic variants of Alpha-actinin-3, Caveolin-1 and vitamin D receptor were investigated in connection with sarcopenia so far." (PMID 33505434, 2020). "They proposed that the A allele of Cav1 G14713A may serve as an pre-indicator for detection of severe sarcopenia and sarcopenia." (PMID 34943268, 2021). "Subsequently, AKT1 and CAV1 have been identified in the interactions between ellagic acid and sarcopenia or muscle atrophy." (PMID 37834245, 2023). "They reported that caveolin-1 (CAV1) may play an important role in the etiology of sarcopenia." (PMID 34943268, 2021). "Common targets between selected components of ECR detected by HPLC and muscle atrophy/sarcopenia were AKT1, as suggested partly by the present results, and CAV1." (PMID 37834245, 2023).
T-cell leukemia (4 papers, 2008 to 2016). A malignant disease of the T-lymphocytes in the bone marrow, thymus, and/or blood. "Most importantly, new in silico predictions were validated in vitro/in vivo using both murine models and gene expression profiles from patients with a T-cell leukemia due to the previously observed role of Cav1 in lymphocytes." (PMID 25538703, 2014). "We focus on the role of CAV1 when overexpressed in T-cell leukemia." (PMID 25538703, 2014). "Additionally, hematopoietic cells that normally do not express caveolin-1 have been shown to augment caveolin-1 levels in certain states of cell activation and it has been suggested that the caveolin-1 expression may serve as a useful marker for the diagnosis of advanced T-cell leukemia." (PMID 18400052, 2008).
Timothy syndrome (4 papers, 2017 to 2023). "Timothy syndrome (CaV1.2G406R) is characterized by an almost complete loss of voltage-dependent inactivation." (PMID 35897673, 2022). "However, the strength of our work is that we show very comprehensive electrophysiological data revealing a pattern very distinctively different from CaV1.2WT and CaV1.2G406R Timothy syndrome variants." (PMID 35897673, 2022). "Of these potential binding partners, we focus on CaV1 because human CACNA1C (which encodes a CaV1 α-subunit) is mutated in Timothy Syndrome (TS), a rare monogenic form of ASD, and polymorphisms linked to CACNA1C are associated with multiple psychiatric disorders." (PMID 35266450, 2022).
ulcerative colitis (4 papers, 2015 to 2022). An inflammatory bowel disease involving the mucosal surface of the large intestine and rectum. "Caveolin-1 inhibits cytokine signal transduction by inhibiting the kinase activity of JAK family members, induces T cell proliferation and secretion of cytokines, and has a protective role in ulcerative colitis." (PMID 35388299, 2022).